VEGFA (vascular endothelial growth factor A)
Diseases named in the same sentence as VEGFA in open-access papers (continued):
Sharing a sentence is not in itself a finding about the gene and the disease.
mesothelioma (34 papers, 2009 to 2025). A usually malignant and aggressive neoplasm of the mesothelium which is often associated with exposure to asbestos. "More encouraging results have been achieved using bevacizumab (Avastin), a humanised anti-VEGFA monoclonal antibody, which demonstrated efficacy in combination with standard of care in many cancers including mesothelioma." (PMID 34226685, 2021). "Here, we observed gremlin-1 mediated upregulation of VEGFA expression in mesothelioma cells." (PMID 29228689, 2017).
cardiomyopathy (33 papers, 2009 to 2026). A disease of the heart muscle or myocardium proper. "By contrast, the day 6 cells displayed an upregulation of pathways related to ribosome, Rap1 signaling, and cardiomyopathy in response to LPS/nig treatment, which included genes such as VEGFA." (PMID 39836544, 2025).
keloid (32 papers, 2007 to 2025). An irregularly shaped, elevated mark on the skin caused by deposits of excessive amounts of collagen during wound healing. "As a ubiquitous cytokine, VEGFA is known to activate various biological functions in multiple cell types and has been implicated in pathological processes such as keloid formation." (PMID 40595500, 2025).
metastatic melanoma (32 papers, 2010 to 2025). A melanoma that has spread from its primary site to another anatomic site. "COL3A1, COL5A2 and VEGFA showed dataset-specific correlations; COL3A1 had strong associations with M1 macrophages, while VEGFA was positively correlated with CD4 T cells in metastatic melanomas." (PMID 40943183, 2025). "Nevertheless, several ongoing clinical trials are testing the combination of anti-VEGFA and anti-PD-1/PD-L1 in metastatic melanoma (NCT02681549, NCT04356729, NCT03175432)." (PMID 35577211, 2022). "In a Phase I study, combined treatment with anti-VEGFA antibody and anti-CTLA-4 antibody achieved favorable outcomes in patients with metastatic melanoma." (PMID 30811474, 2019).
vasculitis (32 papers, 2010 to 2025). "On the other hand, in EAU mice treated with control IgG Ab histopathology showed cell infiltration, vasculitis and granulomas in choroid and retina, demonstrating that treatment with anti-Ang2/VEGFA reduced the level of inflammation in the eye." (PMID 38015876, 2023). "Based on PPI analysis, the overlapped genes with higher degrees in the hub gene network included MAPK1, MAPK3, VEGFA, TNF, and AKT1, implying that they were involved in the process of HXTLF treatment against vasculitis." (PMID 36034958, 2022). "In the histopathology of EAU mice treated with anti-Ang2/VEGFA bispecific Ab mild vasculitis, with no retinal folds and no retinal detachments was observed." (PMID 38015876, 2023).
cataract (31 papers, 2014 to 2025). Partial or complete opacity of the crystalline lens of one or both eyes that decreases visual acuity and eventually results in blindness. "Furthermore, research has revealed that FOXM1 expression is elevated in the lens tissue of cataract patients, which results in TGF-β2 damaging human lens epithelial cells by boosting VEGFA production and initiating the MAPK signaling pathway." (PMID 38662949, 2024).
hyperlipidemia (31 papers, 2013 to 2025). "Wang and the colleagues discovered that astragalus membranaceus, a Chinese medicine herb containing quercetin, could alleviate acquired hyperlipidemia through regulating lipid metabolism, in which the upregulated VEGFA might be one of the key targets." (PMID 37361229, 2023). "More importantly, AKT1, VEGFA, CCND1, ESR1 are the key targets of AM to alleviate hyperlipidemia induced by HFD." (PMID 35267929, 2022). "The results from the PPI analysis showed that the targets for YCWL relating to the treatment of hyperlipidemia mainly involved AKT1, IL6, VEGFA, and PTGS2." (PMID 34746316, 2021). "The results of network pharmacology and bioinformatics analysis in the current study showed that AM might alleviate acquired hyperlipidemia by downregulating the expression of AKT1 and CCND1 and upregulating the expression of VEGFA and ESR1." (PMID 35267929, 2022). "So far, we believe that AM may reduce the expression of AKT1 and CCND1 and increase the expression of VEGFA and ESR1 to alleviate hyperlipidemia induced by HFD." (PMID 35267929, 2022). "Overall, AM alleviated acquired hyperlipidemia through regulating lipid metabolism, and AKT1, VEGFA, CCND1 and ESR1 might be the key targets." (PMID 35267929, 2022). "The previous bioinformatics analysis results showed that AM might alleviate hyperlipidemia by HFD through regulating the expression of four key targets (AKT1, VEGFA, CCND1 and ESR1)." (PMID 35267929, 2022). "In conclusion, AM alleviated acquired hyperlipidemia in mice fed with HFD through regulating lipid metabolism, and AKT1, VEGFA, CCND1 and ESR1 may be the key targets." (PMID 35267929, 2022). "Supportably, it could be seen that AKT1 and CCND1, VEGFA and ESR1 were involved in hyperlipidemia-related diseases and several studies had uncovered the regulation of AM on these genes in different diseases." (PMID 35267929, 2022). "So far, we believe that AM may alleviate hyperlipidemia induced by HFD by downregulating the AKT1 and CCND1 protein levels and upregulating the levels of VEGFA and ESR1 protein." (PMID 35267929, 2022).
hypothyroidism (31 papers, 2012 to 2025). Abnormally low levels of thyroid hormone. "The presence of C-allele in rs833061 and the T-allele in rs3025039 polymorphism of VEGFA were associated with significantly higher risk of hypothyroidism (OR: 10.0 p = 0.041 and OR: 10.5; p = 0.015, respectively)." (PMID 22439647, 2012). "Therefore, as sunitinib acts through the VEGF signaling cascade, authors investigated the influence of VEGFA and VEGFR2 polymorphisms on sunitinib toxicity, highlighting a likely link between sunitinib-induced hypothyroidism." (PMID 26184165, 2015). "We have not studied correlation between SNPs of VEGFA/VEGFR genes and outcomes of therapy due to limited number of cases, but we have found clear associations between two SNPs of VEGFA gene and sunitinib-induced hypothyroidism." (PMID 22439647, 2012).
malaria (31 papers, 2008 to 2025). Malaria is a serious and sometimes fatal disease caused by a parasite that commonly infects a certain type of mosquito which feeds on humans. "For example, while higher levels of HIF-1α mRNA expression have been identified in placental tissues, VEGFA expression was downregulated in malaria patients." (PMID 37375100, 2023). "Several physiological pathways controlled by the circadian timekeeping machinery, including complement and coagulation cascades, interleukin signaling, acute inflammatory response, neutrophil degranulation, and VEGFA-VEGFR2 signaling, are dysregulated in malaria." (PMID 37638001, 2023). "However, increased HIF-1α and VEGFA has not been the consensus in malaria patients." (PMID 37375100, 2023).
pituitary tumor (31 papers, 2010 to 2025). A benign or malignant neoplasm affecting the pituitary gland. "Pituitary tumors also expressed significantly higher levels of angiogenesis growth factors, including VEGFA (4.2-fold), VEGFB (2.2), VEGFC (19.3), PGF (13.4), ANGPT2 (9.2), PDGFA (2.7), PDGFB (10.5) and TGFB1 (3.8) compared to normal pituitary tissue." (PMID 35600354, 2022). "The pituitary contains abundant VEGFA, and VEGFA participated in the formation of the vascular network of a new pituitary tumor, and increased tumoral VEGFA expression was observed during the development of estrogen-induced prolactinoma in rats." (PMID 28163656, 2017). "Therefore, VEGFA likely stimulates angiogenesis in human pituitary tumors in a PGF-dependent manner." (PMID 35600354, 2022). "Compared with normal pituitary tissue, genes with the highest to lowest expression levels in pituitary tumor tissue were VEGFC (19.3-fold, p<0.0001), PGF (13.4-fold, p<0.0001), VEGFA (4.2-fold, p<0.0001) and VEGFB (2.2-fold, p=0.002)." (PMID 35600354, 2022). "Angiogenesis in pituitary tumors is regulated mainly by PGF and VEGFC, not VEGFA and VEGFB." (PMID 35600354, 2022). "Furthermore, we identified PGF and VEGFC, but not VEGFA or VEGFB, as the major angiogenic growth factors regulating angiogenesis in human pituitary tumors." (PMID 35600354, 2022).
Granuloma (30 papers, 2009 to 2025). A compact, organized collection of mature mononuclear phagocytes, which may be but is not necessarily accompanied by accessory features such as necrosis. "In human and rabbit granulomas, VEGFA induces an abnormal and dysfunctional vasculature, which reduces the delivery of low-molecular-weight molecules, potentially affecting chemoprophylactic drug perfusion." (PMID 36561889, 2022). "Among structural cells, the expression of key tissue development genes (MAPK14, GATA6, FOXF1, VEGFA) were markedly elevated in both endothelial and epithelial cell populations derived from MAH granulomas." (PMID 41586350, 2025).
pulmonary edema (30 papers, 2006 to 2025). Accumulation of fluid in the lung tissues causing disturbance of the gas exchange that may lead to respiratory failure. "Moreover, upregulation of the PI3K-Akt signaling pathway promotes expression of IL2, FGF2, and VEGFA, which aggravates inflammation, induces epithelial cell apoptosis, and increases vascular permeability and pulmonary edema." (PMID 33746744, 2020). "Ginseng could reduce the pathologic damage, neutrophil aggregation, proinflammatory factors, and pulmonary edema in vivo and inhibit the PI3K-Akt signaling pathway and MAPK signaling pathway through downregulating expressions of STAT3, VEGFA, FGF2, PIK3CA, MAPK1, and IL2." (PMID 33746744, 2020).
schizophrenia (30 papers, 2011 to 2025). A major psychotic disorder characterized by abnormalities in the perception or expression of reality. "For example, VEGFA marked in angiogenesis is a risk variant specifically in t2d and has also been identified as an important biomarker regulating energy metabolism and vascular blood flow in schizophrenia." (PMID 38573526, 2024). "A study published in 2021 claimed that VEGFA, as an angiogenic and neurotrophic factor, can participate in the regulation of cerebral blood volume and flow in patients with schizophrenia." (PMID 36421842, 2022). "It was described in adult schizophrenia patients (SZP) that concentration of VEGFA, a master angiogenic factor, is decreased." (PMID 29467462, 2018).
pancreatic ductal adenocarcinoma (29 papers, 2013 to 2026). An infiltrating adenocarcinoma that arises from the epithelial cells of the pancreas. "For instance, via its competing endogenous RNA activity on hsa-miR-29b-3p, LINC00511 induced the expression of VEGFA leading functionally to pancreatic ductal adenocarcinoma progression." (PMID 32698787, 2020). "LINC00511 competitively endogenously inhibits hsa-miR-29b-3p activity to upregulate vascular endothelial growth factor A (VEGFA), promoting pancreatic ductal adenocarcinoma (PDAC) stemness." (PMID 37888204, 2023).
gastric adenocarcinoma (28 papers, 2005 to 2025). "Our results revealed that MBNL3 exhibited higher expression, and MBNL3 acted as a target of miR-302e to facilitate cell proliferation, invasion, and angiogenesis of gastric adenocarcinoma through the AKT/VEGFA pathway." (PMID 38955795, 2024). "In conclusion, MBNL3 acted as a target of miR-302e to facilitate cell proliferation, invasion, and angiogenesis of gastric adenocarcinoma through the AKT/VEGFA pathway." (PMID 38955795, 2024). "MBNL3 was revealed to act as a target of miR-302e to facilitate cell proliferation, invasion, and angiogenesis of gastric adenocarcinoma through the AKT/VEGFA pathway." (PMID 38955795, 2024). "Several in vitro studies, including our own observations (manuscript submitted), show that in co-cultures H. pylori induces the expression of ANGPT2, VEGFA and other angiogenesis-related factors in gastric adenocarcinoma cell lines." (PMID 36874142, 2023). "The lncRNA TUG1 enhances the malignant behavior of gastric adenocarcinoma by regulating miR-29c-3p to upregulate VEGFA." (PMID 35813862, 2022). "In genomics, ERBB2, VEGFA, GATA4 and GATA6 gene amplifications were frequently observed in Barrett’s adenocarcinomas, which strongly resemble the chromosomally unstable variant of gastric adenocarcinoma." (PMID 33087057, 2020).
tuberculosis (28 papers, 2006 to 2025). A chronic, recurrent infection caused by the bacterium Mycobacterium tuberculosis. "Elevated VEGFA levels have been linked to granulomatous inflammation observed in conditions such as tuberculosis, sarcoidosis, and inflammatory bowel disease." (PMID 39680552, 2024). "In another clinical study of 28 patients with tuberculosis (Tb), it was found that the levels of VEGFA were an important determinant of DS-TB patients’ clinical status." (PMID 37215213, 2023). "Module1 primarily participated in Antigen processing and presentation; Module2 regulated VEGFA VEGFR2 signaling; Module3 was enriched in immune response to tuberculosis; Module4 regulated Proteasome." (PMID 40170854, 2025). "To validate the expression of VEGFA and NR3C1, we performed IHC to examine 12 mediastinal lymph node tissues from pulmonary sarcoidosis patients and 13 mediastinal lymph node tissues from tuberculosis patients." (PMID 34055877, 2021).
hematoma (27 papers, 2015 to 2025). A hematoma is a collection of blood from a vascular structure into an extravascular space. "In our smokers’ hematomas, we detected a slight reduction in VEGFA expression correlating to the previously highlighted study." (PMID 35621464, 2022). "Results of main influencing factors PDGF-BB, VEGFA, Angpt1, MMP9, and GM-CSF were additionally confirmed by gene expression analysis, whereas except for GM-CSF all genes were expressed less in the smokers’ hematomas." (PMID 35621464, 2022).
Hypoglycemia (27 papers, 2007 to 2026). A decreased concentration of glucose in the blood. "Soluble isoforms of NRP1 (sNRP1) also exist without transmembrane or cytoplasmic domains, expressing only the extracellular domains which allow them to bind NRP1 ligands; therefore, the plasma levels of NRP1 ligands (VEGFA and SEMA3A) were determined in response to insulin-induced hypoglycemia." (PMID 34248841, 2021).
inflammatory bowel disease (27 papers, 2013 to 2025). A spectrum of small and large bowel inflammatory diseases of unknown etiology. "Vascular endothelial growth factor-A (VEGF-A) is a known biomarker of angiogenesis in patients with inflammatory bowel disease." (PMID 40927726, 2025).
pancreatic adenocarcinoma (27 papers, 2010 to 2026). "In murine 4T1 and LLC cells (breast and lung tumor, respectively), as well as in human CAPAN-1 pancreatic adenocarcinoma, the VEGFA and VEGFC IRESs are activated after 24 hr of hypoxia whereas the EMCV IRES is not activated." (PMID 31815666, 2019).
retinoblastoma (27 papers, 2008 to 2025). A malignant tumor that originates in the nuclear layer of the retina. "The cells were treated with CM collected from Y‐79 human retinoblastoma cell line, or VEGFA‐stimulated in order to reproduce the angiogenic‐switch." (PMID 31369203, 2019). "The tube total length and the number of branch points from single HREC were both significantly decreased compared to cells treated with retinoblastoma CM or VEGFA." (PMID 31369203, 2019). "In retinoblastoma tumors, stemness‐related SOX2 is usually accompanied by higher VEGFA expression and tumor invasion." (PMID 36708044, 2023).
Miscarriage (26 papers, 2012 to 2025). A pregnancy that ends at a stage in which the fetus is incapable of surviving on its own, defined as the spontaneous loss of a fetus before the 22th week of pregnancy. "An association was found between the presence of polymorphism -2578C>A of the VEGFA gene in the genome with the miscarriage risk." (PMID 30746337, 2018). "The miscarriage risk decreased with simultaneous presence of the VEGFA -634 CG and VEGFA -2578CC genotype (OR 0.38, 95% CI 0.19–0.78, p=0.01) and VEGFA -2578CC, VEGFA -634CG, TGFB1 936CC genotype (OR 0.45, 95% CI 0.21–0.96, p=0.057)." (PMID 30746337, 2018). "The current research was conducted to investigate the association of VEGFA gene polymorphic variants -2578C>A (rs699947) and -634G>C (rs 2010963) and TGFB1 gene 915G>C (rs1800471) and gene expression level with miscarriage in the first trimester." (PMID 30746337, 2018). "Other studies have reported a substantial decrease in trophoblast cell numbers in early RSA patients, along with down-regulation of STAT3 and its downstream target genes cyclin D1 (CCND1) and vascular endothelial growth factor A (VEGF) in miscarriage tissues (chorionic villi and decidua)." (PMID 38235138, 2023). "The MDR analysis data have shown the significance for two-locus and three-locus models of the VEGFA and TGFB1 genes with miscarriage." (PMID 30746337, 2018). "Literature data on allele frequencies and genotypes investigated VEGFA and TGFB1 SNPs in chorionic tissue in miscarriage in the first trimester are absent." (PMID 30746337, 2018). "No changes of VEGFA expression were found in miscarriage compared with a physiological pregnancy." (PMID 30746337, 2018).
serous ovarian cancer (26 papers, 2006 to 2025). "A very recent study in high grade serous ovarian carcinoma documented the correlation of VEGFA levels and poor prognosis, rendering VEGFA an ideal candidate to stratify patients prone to drug resistance upon mTOR pathway upregulation." (PMID 27090655, 2016). "Stratifying drug resistant high grade serous ovarian cancer via VEGFA, and specifically treating with mTOR inhibitors in case of activation of the pathway may allow adding precision for overcoming resistance to first line therapy." (PMID 27090655, 2016). "Among these, DH1, VEGFA, EPCAM, ITGB2, and CLDN7 had the highest correlation scores with serous ovarian cancer." (PMID 36980477, 2023). "High expression of VEGFA and ZNF385A correlate with poor survival of patients with serous ovarian carcinoma." (PMID 29503225, 2018). "Similarly, a study on serous ovarian cancer cell lines demonstrated that PIK3R1 downregulation induced the expression of antiapoptotic BCL2, as well as genes involved in cell cycle progression (CCNB1) and metastasis (MMP9 and VEGFA)." (PMID 39858051, 2025).
systemic lupus erythematosus (26 papers, 2012 to 2025). An autoimmune multi-organ disease typically associated with vasculopathy and autoantibody production. "Urinary VEGFA levels are significantly higher in lupus nephritis patients than in lupus patients without renal damage." (PMID 33987885, 2021).
brain injury (25 papers, 2014 to 2025). Acute and chronic (see also brain INJURIES, CHRONIC) injuries to the brain, including the cerebral hemispheres, CEREBELLUM, and brain STEM. "Furthermore, SHD promotes the level of IL-6 and APP proteins in rats after ischemic brain injury and reduces the level of AKT1 and VEGFA proteins." (PMID 35097126, 2022).